RN7SL849P (RNA, 7SL, cytoplasmic 849, pseudogene)
Gene: Miscellaneous RNA gene on chromosome 9 (12,764,761 to 12,765,055, reverse strand). Ensembl gene ENSG00000243115.
Homologues: Orthologues: chimpanzee Metazoa_SRP (98% identical), macaque Metazoa_SRP (92% identical). Paralogues in human: RN7SL1 (79% identical), RN7SL2 (79% identical), RN7SL597P (78% identical), RN7SL3 (77% identical), RN7SL660P (77% identical), RN7SL296P (76% identical), RN7SL492P (76% identical), RN7SL507P (76% identical), RN7SL655P (76% identical), RN7SL797P (76% identical), RN7SL125P (76% identical), RN7SL220P (76% identical), and 703 more.